TH (tyrosine hydroxylase)
Diseases named in the same sentence as TH in open-access papers (continued):
Sharing a sentence is not in itself a finding about the gene and the disease.
neuroblastoma (continued). "Using the TH-MYCN neuroblastoma mouse model in which human MYCN is expressed under control of the mouse tyrosine hydroxylase promoter, we are able to generate mouse neuroblastoma tumors with high penetrance, which are genetically, histologically, and morphologically similar to human neuroblastomas." (PMID 26029667, 2015). "However, to study neuroblastoma disease in vivo, several mouse models have been developed through genetic engineering, the TH-MYCN transgenic mouse model (which expresses human MYCN specifically in neuroblasts under the control of the tyrosine hydroxylase (TH) promoter) being the most widely used." (PMID 36675105, 2023). "However, since PHOX2B and TH were markers of the adrenergic (ADR) super-enhancer state, and were not universally expressed by neuroblastoma cells, a further understanding of the gene expression landscape of these neuroblastoma CTCs, including markers of the mesenchymal (MES) state, was required." (PMID 36176417, 2022). "Since MES cells do not express the typical markers (PHOX2B, TH, or DBH) used in clinical routine to characterize neuroblastoma cells, their detection requires the use of other markers or technics." (PMID 34200747, 2021). "Initial evaluation of the neuroblastoma SH-SY5Y cell line demonstrated moderate dopamine–hydroxylase activity and low levels of choline acetyl-transferase, acetyl-cholinesterase, and butyryl-cholinesterase, as well as tyrosine hydroxylase activity and nor-adrenaline (NA) release." (PMID 37589832, 2024).
Parkinsonism (91 papers, 2009 to 2026). Characteristic neurologic anomaly resulting from degeneration of dopamine-generating cells in the substantia nigra, a region of the midbrain, characterized clinically by shaking, rigidity, slowness of movement and difficulty with walking and gait. "To summarize, aging-related parkinsonism cannot be explained by loss of TH protein or DA tissue levels in striatum, given the high variability of loss across studies and that TH or DA loss does not reach the accepted consensus of 80% loss associated with the onset of motor symptoms in PD." (PMID 38256204, 2024). "Since lack or dysfunction of TH results in dopamine deficiency and parkinsonism, induction of TH expression in striatal neurons may explain the observed rescue of PD phenotypes in mice and provide therapeutic benefits for PD patients." (PMID 39714464, 2024). "Because TH expression is significantly attenuated in the brains of MPTP-induced PD model, we evaluated TH levels to confirm the establishment of a chronic MPTP-induced Parkinsonism mouse model and the protective effects of crocetin." (PMID 33101635, 2020). "Accordingly, experimental studies using distinct parkinsonism models have commonly focused on the density of tyrosine hydroxylase-positive (TH+) neuronal cell bodies in the SNpc as a parameter to assess the PD progression severity and correlate it with motor symptoms." (PMID 40751268, 2025). "EPO administration could rescue the expression of TH in rats in which parkinsonism was induced with rotenone or 6-hydroxydopamine, together with decreased levels of tumor necrosis factor alpha in the same brain areas affected by PD." (PMID 33467745, 2021). "Given that the TH expression in the brains is an important marker of the MPTP-induced PD model, the TH levels were used to evaluate the protective effects of crocetin on MPTP-induced Parkinsonism mouse model." (PMID 33101635, 2020).
schizophrenia (49 papers, 2009 to 2026). A major psychotic disorder characterized by abnormalities in the perception or expression of reality. "Strikingly, injecting FA into the VTA as well as administering MK-801 induced schizophrenia-like behaviors associated with reduced DA levels and low activity of tyrosine hydroxylase (TH) and monoamine oxidase (MAO) in the PFC." (PMID 40140372, 2025). "Tyrosine hydroxylase (TH) is a key-component of dopamine metabolism and has been implicated in schizophrenia, antipsychotic-induced extrapyramidal side-effects and RLS." (PMID 29587340, 2018). "In this study, we investigated the association between antipsychotic-induced RLS and the TH gene Val81Met polymorphism, among schizophrenia patients who took antipsychotics." (PMID 20046397, 2009). "TH deficiency leads to impaired synthesis of dopamine and alterations in its activity, which are involved in disorders such as Parkinson’s disease (PD) and schizophrenia." (PMID 36966421, 2023). "Moreover, copper-containing enzymes, including dopamine-beta-hydroxylase and tyrosine hydroxylase, are linked to the synthesis of dopamine and norepinephrine, which have been involved in the etiology of schizophrenia." (PMID 26186003, 2015). "TH gene variants have been associated with schizophrenia in 6 out of 19 studies." (PMID 25073638, 2014). "We investigated the hypothesis that TH Val81Met polymorphism can influence susceptibility to tardive dyskinesia (TD) in schizophrenia." (PMID 20046383, 2009). "Likewise, the detection of a link between schizophrenia-related sleep disorders and genes implicated in neurotransmitter metabolism (TH and HNMT) and signal transduction (GNB3 and BTBD9) emphasizes the central role of neurotransmission disturbances in the emergence of schizophrenia symptomatology." (PMID 29587340, 2018). "The proportion of neurons co-expressing transcripts for TH and vesicular glutamate transporters was reduced with marginal significance in schizophrenia compared to controls." (PMID 39397771, 2025). "Increased tyrosine hydroxylase mRNA expression, dopamine synthesis, and serotonin production are seen in individuals with schizophrenia." (PMID 39199302, 2024). "The TH gene, which is involved in dopamine regulation, has been extensively studied in relation to neuropsychiatric diseases, including schizophrenia, bipolar disorder, depressive disorder, and anxiety disorder." (PMID 39766792, 2024). "A previous study also showed an increase of TH expression in the nucleus accumbens of methamphetamine‐treated mice, which are considered a model for mania, schizophrenia, and addiction, showing enhanced synaptic dopamine levels." (PMID 36794530, 2023). "When counting double-labelled GABRA3+/TH+ and single-labelled GABRA3−/TH+ neurons in 3 control and 3 high inflammatory/schizophrenia cases, we identified GABRA3 expression in 98% of TH+ neurons, irrespective of diagnostic group." (PMID 34174930, 2021). "Though dysfunctions of the dopaminergic system are involved in neurological disorders, such as Tourette’s syndrome, schizophrenia, pituitary tumors, PD, and DRD, the loss of nigrostriatal tyrosine hydroxylase (TH) protein is distinctive in PD and DRD." (PMID 32471089, 2020). "It has been reported that the expression of TH, the rate-limiting enzyme of dopamine synthesis, is increased in the substantia nigra (SN) of schizophrenia patients." (PMID 32303857, 2020). "Post-mortem studies from schizophrenia patients have shown a reduced expression of the rate-limiting enzyme of dopamine synthesis, tyrosine hydroxylase (TH) in midbrain dopaminergic neurons." (PMID 32303857, 2020). "Tyrosine hydroxylase (TH), the enzyme involved in the synthesis of DA, has been reported to be increased in lymphocytes of schizophrenia patients." (PMID 28358316, 2017).
schizophrenia (continued). "Dopaminergic anomalies are a well-known component of schizophrenia pathology, and previous findings from our laboratory have shown significant reductions in tyrosine hydroxylase (TH) protein levels within rostral regions of the SN/VTA in schizophrenia." (PMID 24941246, 2014). "In previous studies, we reported that tyrosine hydroxylase (TH), the dopamine synthesis rate-limiting enzyme, is over-expressed in peripheral blood leukocytes (PBLs) of drug-free schizophrenia patients." (PMID 24086483, 2013). "Here, we examined DA-containing neuronal structures of the ventral tegmental area (VTA) of an autopsy case of disorganized type of schizophrenia (75-year-old female), using tyrosine hydroxylase (TH) immunohistochemistry." (PMID 22937337, 2011). "Association between IGF2 enhancer hypomethylation in prefrontal cortex neurons and increased tyrosine hydroxylase protein has been established in schizophrenia and bipolar patients, indicating epigenetic regulation of dopamine synthesis through IGF2 methylation." (PMID 38516266, 2024). "Considering these previous reports and our results, the delicately balanced regulation of dopamine transmission including TH may play an important role in the drug therapy of PD, schizophrenia, and BPD." (PMID 36794530, 2023). "These neuroimaging results matched earlier immunocytochemical reports investigating tyrosine hydroxylase (TH) labeling (a marker of dopaminergic synapses) on postmortem tissues from both treatment resistant and treatment responder schizophrenia as well as control brains." (PMID 36979877, 2023). "TH, an enzyme important for DA synthesis, implicates schizophrenia." (PMID 35062349, 2022). "Using a similar approach, a hypomethylated locus at the IGF2 gene, identified in neurons of patients with schizophrenia or bipolar disorder, was shown to physically interact with the promoter of the tyrosine hydroxylase (TH) gene, coding for the rate-limiting enzyme in dopamine synthesis." (PMID 32248367, 2020). "However, through the medium of two genes analogical to the human gene for tyrosine hydroxylase, T. gondii also directly enhances dopaminergic activity that is critical for the development of schizophrenia, autism, and other mental disorders." (PMID 32132937, 2019). "Additionally, our study did not compare subregions (VTA versus substantia nigra) or dorsal or ventral distribution within these regions and a recent study identified reductions in TH protein in subregions of the midbrain in schizophrenia." (PMID 28094812, 2017). "In the midbrains of individuals with schizophrenia, we observed potential differences in the proportions of two (sub)populations of excitatory neurons, two subpopulations of inhibitory neurons, one ‘mixed’ subpopulation, and one subpopulation of TH-expressing neurons." (PMID 39397771, 2025). "Decreased NURR1 expression can precede downregulation of BDNF mRNA and is paralleled by reductions in TH in cultured mesencephalic neurons, which are less resilient to neurotoxicity with NURR1 deficiency, reflecting that there may be specific impediments to dopamine neuron survival in schizophrenia." (PMID 40335479, 2025). "TH and aromatic acid decarboxylase (AADC) mRNA and TH protein were unchanged in the midbrain in schizophrenia compared with controls." (PMID 28094812, 2017). "TH and the synaptic dopamine transporter (DAT) proteins were examined in post-mortem midbrain (26 antipsychotic-treated schizophrenia cases per 27 controls) using immunoblotting." (PMID 28094812, 2017). "We hypothesised that TH and AADC mRNA would be increased in the midbrain in schizophrenia with a corresponding increase in TH protein in the midbrain." (PMID 28094812, 2017). "Similarly, in bipolar disorder, there are reduced tyrosine hydroxylase (TH) mRNA levels, increased VMAT2 signal, and increased anatomical volume of the SN, thus highlighting the importance of the SN in schizophrenia and bipolar disorder pathophysiology." (PMID 41567988, 2026).
schizophrenia (continued). "Both dopamine receptors are highly involved in schizophrenia, however, hyperlocomotion in animal models can be also triggered directly via NMDA antagonists, which was confirmed on dopamine-deficient mice lacking tyrosine hydroxylase." (PMID 33101067, 2020). "In vivo imaging studies indicate an increased presynaptic dopamine synthesis capacity in striatal terminals and cell bodies in the midbrain in schizophrenia; however, measures of the dopamine-synthesising enzyme, tyrosine hydroxylase (TH), have not identified consistent changes." (PMID 28094812, 2017).
Anxiety (41 papers, 2014 to 2026). Intense feelings of nervousness, tension, or panic often arise in response to interpersonal stresses. "Those involving THAP1 (n = 1) and TOR1A (n = 1) were linked with myelopathies, while SGCE variants (n = 2) were associated with depression, anxiety and myoclonus, and hemiplegia for the single overlapping TH variant." (PMID 35925398, 2022). "Unilateral 6-OHDA injection in the medial forebrain bundle (MFB) led to anxiety-like behavior with a 96% loss of TH in the STR and 87% loss of neurons in the SNc." (PMID 34204380, 2021). "NE deficiency due to TH variants leads to numerous brain dysfunctions, especially anxiety and depression." (PMID 34054692, 2021). "The higher anxiety found in female mice could also be linked to the estrous cycle because estrogen up-regulates TH gene transcription and mRNA expression in the LC, as well as the noradrenaline release in multiple brain areas." (PMID 37770907, 2023). "Similarly, bilateral striatal injection of 6-OHDA to mice, resulting in ~70% loss of striatal TH, produces only modest gait alterations but does result in changes indicative of depression and anxiety." (PMID 32973447, 2020). "These include tyrosine hydroxylase (TH), the rate-limiting enzyme in DA synthesis, and cholesystekinin (Cck), a peptide negatively associated with DA activity in vivo, which has been implicated in anxiety and drug response." (PMID 26793129, 2015). "Some animal studies suggest that BoNT undergoes retrograde transport and can alter the neurotransmitter systems such as dopamine, serotonin, and GABA, all of which are critical in anxiety and mood regulation, which could be associated via TH-mediated generation of L-DOPA." (PMID 41008276, 2025). "The activity of tyrosine hydroxylase (TH) regulates dopamine, whose levels and metabolites in the mouse brain are related with anxiety-like behavior." (PMID 36614124, 2022). "Here, we demonstrate that specific activation of the terminals within the mPFC from VTA TH neurons by optogenetic manipulation in mice rescues anxiety‐like behavior induced by chronic stress." (PMID 33112032, 2021). "Optogenetic activation of VTA TH terminals in the mPFC rescued anxiety‐like behavior induced by chronic stress." (PMID 33112032, 2021). "In the same model, the anxiety-like behavior was also present in the open-field test and EPM, and they were alleviated by hesperidine, which also reduced TH positive neurons loss." (PMID 34204380, 2021). "Inhibitions of anxiety-like behavior and reductions in tyrosine hydroxylase mRNA expression in the VTA and tyrosine hydroxylase protein expression in the NAc by acupuncture in ethanol-withdrawn rats confirmed these results." (PMID 30416533, 2018). "TH is an enzyme involved in the response to morphine withdrawal-related psychopathological conditions, such as depression and anxiety." (PMID 24527041, 2014). "Here, tyrosine hydroxylase (TH): Cre mice received 5 Hz, 5 ms pulses of blue light for 3 min while behaving in the elevated zero maze—a validated behavioral test used to assess anxiety-like behaviors." (PMID 24592222, 2014). "The authors also found an increase in cortical tyrosine hydroxylase expression and downregulation of monoamine oxidase-A, indicating a change in monoaminergic pathways that could contribute to anxiety reduction." (PMID 39857431, 2025). "The stress‐related hormones, tumor‐related cytokines, the tyrosine hydroxylase (TH)–positive neurons and their fibers, dopamine receptor–positive cells, and anxiety level were measured using ELISA, immunohistochemical staining, fluorescence in situ hybridization, and behavioral test, respectively." (PMID 33112032, 2021). "Repeated injections of MPTP at 17.5 mg/kg led to some reduction in the number of nigrostriatal TH-positive neurons, causing depression- and anxiety-like behavior without any obvious induction of motor deficits." (PMID 31427934, 2019).
Anxiety (continued). "Psychological stressors may cause affective disorders, such as depression and anxiety, by altering expressions of corticotropin releasing factor (CRF), serotonin (5-HT), and tyrosine hydroxylase (TH) in the brain." (PMID 25881143, 2015). "Our results showed that TH, DAT and DA2 expression was significantly increased in the amygdala of female ERβ deficient mice, suggesting a role for ERβ in monoamine neurotransmission and anxiety behaviour in mice and corresponds well with the results of other authors." (PMID 36650256, 2023). "At the behavioral level, anxiety, sociability, and parental behavior were examined, while at the molecular level, brain expression of AVPV TH and plasma testosterone were measured." (PMID 36818606, 2023). "Available data from multiple studies suggest that increased levels of TH, DA2, and AChRM1 may constitute an anxiolytic mechanism to alleviate anxiety, whereas DAT overexpression seems to be anxiogenic." (PMID 36650256, 2023). "The available data from various studies suggest that increased levels of TH, DA2 and AChRM1 may be an anxiolytic mechanism to reduce anxiety, whereas DAT overexpression appears to be anxiogenic." (PMID 36650256, 2023). "HI injury regardless of its severity, was found to reduce anxiety-like behavior in Sprague-Dawley rats due to decreased activity of tyrosine hydroxylase in the substantia nigra." (PMID 29018327, 2017). "We assessed the loss of TH+ cells and TH fibers associated with different doses of 6-OHDA, and examined dose-dependent motor symptoms (including gait changes), non-motor symptoms (anxiety-like behaviors, depression-like behaviors), mitochondrial dysfunction and glial cell activation." (PMID 38355892, 2024). "Given that CeMCRH neurons play a critical role in the modulation of anxiety and that LPGiCA neurons are involved in regulating autonomic responses to various stressors, we chose to focus on exploring whether PRV-infected CeM and LPGi neurons express CRH and TH, respectively." (PMID 37847562, 2023). "Thus, based on the present observations, a hypothesis concerning the mechanisms underlying the behavioral effects of AGN can be proposed in which the depression- and anxiety-induced behaviors occur via dysregulation of the HPA axis and the neurochemical interactions between CRF and TH in the brain." (PMID 26138544, 2015). "While we don’t know its comparative level in the PFC, the level of TH, ERK and D2DR were all unchanged in the PFC, suggesting that dopaminergic signaling in this region is likely not responsible for anxiety-like behaviors of the Kv1.3−/− mice." (PMID 29615878, 2018).